STAT3 (signal transducer and activator of transcription 3)
Diseases named in the same sentence as STAT3 in open-access papers (continued):
Sharing a sentence is not in itself a finding about the gene and the disease.
tumor (continued). "As the intersection of several tumorigenic signaling pathways, STAT3 is considered to have an important role in tumor cells and the tumor microenvironment." (PMID 35296801, 2022). "STAT3 has been identified as main factor in increased PD-L1 expression on tumor cells, which is targeted by anti-PD-1 therapy." (PMID 35053465, 2022). "As a result, upon inhibition of Stat3, tumour cells, having high E2F levels, will succumb to apoptosis." (PMID 36010614, 2022). "Previous studies have implicated tumor suppressor NDRG1 in mediating iron chelation mechanism of action through the inhibition as EGFR, TGF-β, and STAT3." (PMID 36213122, 2022). "CRC murine models bearing IL-6-secreting iCAFs with constitutive STAT3 activation exhibited reduced tumor growth after inhibition of angiogenic signaling, suggesting that sustained angiogenesis at least partially depends on IL-6 and STAT3 signaling." (PMID 36436127, 2022). "STAT3 is a central transcription factor involved in the cross-talk between tumor cells and immune cells in the tumor microenvironment." (PMID 35917644, 2022). "STAT3 both drives proper memory differentiation at early stages and modulates T-cell metabolism at the tumor site, contributing to antitumor response." (PMID 35270020, 2022). "STAT3 binds to the promoters of its target genes to induce tumor cell migration, growth, and differentiation and plays an important role in the development of a variety of tumors." (PMID 35237519, 2022). "Numerous studies have shown that STAT3 serves a significant role in multiple aspects, including tumor invasion, migration, metastasis, and angiogenesis." (PMID 36207761, 2022). "STAT3 knockdown by siRNA prevented tumor cell proliferation and blocked CSC-mediated immunosuppression." (PMID 35740975, 2022). "On the one hand, we summarize the current knowledge on how tumor cell-intrinsic STAT3 drives the evasion from NK cells." (PMID 35865518, 2022). "Curcumin inhibited tumor-derived IL-6 to inhibit dendritic cell STAT3 and restore dendritic cell-mediated stimulation of T cell immunity." (PMID 36700235, 2022). "Although the role of signal transducers and activators of transcription (STAT3) in cachexia due to the association of circulating IL-6 and muscle wasting has been extensively demonstrated, the effect of resistance training on STAT3 in mediating muscle atrophy in tumor-bearing mice is unknown." (PMID 35847939, 2022). "At the same time, high expression of STAT3 is corrected with an advanced tumor grade and poor prognosis." (PMID 36295083, 2022). "Mechanistic studies revealed that the IL-9/STAT3/fatty acid oxidation pathway rendered Tc9 cells with reduced lipid peroxidation and resistance to tumor- or ROS-induced ferroptosis in the TME." (PMID 35192544, 2022). "STAT3 is constitutively activated in various of cancer types and plays a vital role in tumor angiogenesis and expansion." (PMID 36217202, 2022). "A study by Iwahasi17 suggested that HCC tumor malignancy, through the IL-6/STAT3 pathway, is affected by the activation of hepatic stellate cells." (PMID 37829248, 2022). "STAT3 is a key oncogenic transcriptional factor that mediates signal transduction and regulates the transcription of target genes contributing to tumor development and progression." (PMID 34976223, 2022). "Mass spectrometry analysis demonstrated that the GDEs contain a variety of contents, including members involved in the signal transducer and activator of transcription 3 (STAT3) pathway that functionally mediate this pro-tumor immune-suppressive switch." (PMID 35600367, 2022). "Decreased p-STAT3 expression was observed in tumor tissues derived from MBNL1-overexpressing NTC/T2 null cells compared with the control cells." (PMID 36217202, 2022). "To determine the necessity of these signaling cascades for the ability of EVsMMA-MRC5 to drive EMT, we blocked their activation in A549 tumor cells using the TGFβR or STAT-3 inhibitors, SB431542 and cryptotanshinone, respectively." (PMID 36266345, 2022).
tumor (continued). "Tumor-associated macrophages and cancer-associated fibroblasts secrete IL-6 that favors via JAK/STAT3 the migration and invasion of CRC cells." (PMID 36139106, 2022). "A recent study has shown that a new small-molecule inhibitor of STAT3 suppresses tumor growth and metastasis and significantly prolongs the survival of tumor-bearing mice in animal models of PDAC." (PMID 35565185, 2022). "To better understand the role of STAT3 in the tumor microenvironment, we compared HCC samples that were positive or negative for STAT3-expressing immune cells." (PMID 35267462, 2022). "For example, fatty acids can enhance STAT3 palmitoylation and directly activate STAT3 in synergy with cytokine stimulation, thus promoting the tumor spheres formation and tumorigenesis." (PMID 36267966, 2022). "Current research has revealed that STAT3 is involved in the immune escape of tumor cells as it suppresses anticancer immune cells and activates pro-cancer immune cells." (PMID 36313702, 2022). "A new study has shown that the inhibition of nuclear factor-kappa B (NF-κB) activity and the increase of STAT3 activity in Mφs represent a tumor-mediated mechanism that triggers M1/M2 deviation." (PMID 35145526, 2022). "Differences in the frequency of immune cell populations were analyzed based on tumor type, location within the TME (brain-tumor interface/infiltrating edge, tumor, and necrosis), and p-STAT3 expression." (PMID 35316217, 2022). "Consistently, tumor proliferation, apoptosis, and STAT3 phosphorylation, as well as gene expression of Ereg, IL-6, and IL-11, were not significantly altered in Villin:Cre-Phd2fl/fl mice as compared with the controls." (PMID 36509284, 2022). "In lung cancer, mucosa-associated lymphoid tissue 1 MALT1) cross-talks with NF-κB and STAT3 to develop an inflammatory tumor microenvironment." (PMID 36438839, 2022). "This correlation strongly suggests that the growth of 4T1 cancer cells in the tumor is inhibited after treatment with mc-1Stat3 through STAT3 targeting." (PMID 35847174, 2022). "In this context, unrepaired DSBs lead to the constitutive activation of ATM kinase, which in turn triggers the downstream NF-kB- and STAT3-mediated survival pathways, resulting in cancer stemness maintenance and post-therapy repopulation of the tumor." (PMID 35408878, 2022). "Signal transducers and activators of transcription 3 (STAT3) is a transcription factor that is important for tumor development in various cancers, including GBM." (PMID 35267626, 2022). "FLU administration also inhibited breast CS-like cells-enriched TNBC tumor growth, angiogenesis, and metastasis to lung and liver through suppressing STAT3 activation." (PMID 35008943, 2022). "The positive regulation of cancer by B cells in the TIME has been directly linked to B cells that have signal transducer and activator of transcription 3 (STAT3) activated, which eventually promotes tumor growth by contributing to a proangiogenic environment." (PMID 35628597, 2022). "In cancer, STAT3 is mainly described as a tumor promoter driving tumor cell proliferation, resistance to apoptosis, angiogenesis and metastasis and aberrant activation of STAT3 is associated with poor prognosis." (PMID 35865518, 2022). "For example, Activated Stat3 enters the nucleus of cells and binds to the promoter of PD-L1 gene and induces the expression of PD-L1 on the surface of tumor cells." (PMID 36454780, 2022). "Treatment with Stattic, a STAT3 inhibitor, significantly reduced the weight of the tumor xenografts." (PMID 36230984, 2022). "IL6 is an inflammatory cytokine that modulate growth and differentiation in tumor cells through STAT3 signaling pathway." (PMID 35399006, 2022). "Whilst STAT3 is thought to be significantly involved in tumor biology, STAT1 is thought to have a role in pathogen defense, growth inhibition and apoptosis." (PMID 35053592, 2022).
tumor (continued). "EV-associated IL-6 functions as a stroma-tumor messenger, activating the JAK/STAT3 and TGFβ signaling pathways in tumor cells and promoting pro-aggressive behaviors." (PMID 36266345, 2022). "While M2 polarization can activate the STAT3 pathway, enhance the tumor enhancement of M2, and thus promote the growth and migration of PC cells." (PMID 35145526, 2022). "The current evidence derived from STAT3 dimerization and methylation inhibition to in vivo tumor suppression make C16 an attractive strategy for further development and utilization, such as improving solubility, bioavailability, and tumor‐targeted delivery." (PMID 35843865, 2022). "Constitutively-active Stat3 promotes primary tumor development and the progression to therapy resistance." (PMID 35276290, 2022). "Although confounded by potential leptin effects on tumor cells, this study demonstrates the positive role of T-cell STAT3 signaling in antitumor immunity." (PMID 35270020, 2022). "In summary, IL-6 serves as a critical factor involved in the immunosuppression of T cells and tumor cells mediated via the IL-6/JAK1/Stat3 signaling pathway." (PMID 35550592, 2022). "We also observed a significant reduction in tumor diameter with inhibitors of STAT3 and NF-κB (FLLL31 and JSH23, respectively), showing that these transcription factors are likely involved in tumor growth." (PMID 36551683, 2022). "Immunofluorescent immunohistochemistry (IHC-IF) staining of pSTAT3 and pSRC on these tumor slices showed that STAT3 activity and SRC activity were dramatically downregulated by Niraparib treatment." (PMID 36324587, 2022). "It has been reported that hypoxia induces impairment of the NK cell cytotoxicity against tumor cells, and this effect is associated with the reduction in the phosphorylation of ERK and STAT3." (PMID 35565420, 2022). "Over-activation of STAT3 in tumor cells also induces the production of IL-6, resulting in a positive feedback loop." (PMID 36591515, 2022). "Literature has shown that IL-6 can inhibit the immune-killing ability of NK cells to tumors by activating the JAK/STAT3 pathway, thereby promoting tumor progression." (PMID 36384635, 2022). "Inhibition of STAT3 signaling was associated with increased levels of CCL5 and thereby enhanced lymphocyte infiltration into the tumor." (PMID 35865518, 2022). "Forkhead box O1 (FoxO1) silencing enhances NPC progression, whereas STAT3 silencing prevents tumor progression." (PMID 36313702, 2022). "Collectively, polymer X induced tumor spheroid formation ability and STAT3 signaling activation in the candidate cancer cells." (PMID 36359204, 2022). "We then profiled tumor tissues for Stat3 activity and Stat3 target gene expression as pharmacodynamic markers of therapeutic response." (PMID 35276290, 2022). "The induction of STAT3 by IL-6 or stress factors leads to progress in the self-renewal of prostate CSCs and tumor-propagation." (PMID 36359888, 2022). "IL‐11 secreted by CAFs, due to TGF‐β exposure, triggers glycoprotein 130 (GP130)/STAT3 signaling in tumor cells, thereby demonstrating the prometastatic role of IL‐11 in CRC." (PMID 35791509, 2022). "In summary, our study uncovered the key role of the RSL1D1/RAN/STAT3 regulatory axis in autophagy and tumor progression in CRC, highlighting a new target for preventing and treating CRC." (PMID 35013134, 2022). "Our in vitro data also showed that when the microbiota, cancer cells, and immune cells were present simultaneously, the abundance of M2-TAMs, the level of IL-17A secreted by γδ T cells, and the phosphorylation level of STAT3 in tumor cells peaked." (PMID 36000726, 2022).
tumor (continued). "Most importantly, inhibition of Cad11 would induce apoptosis (through Stat3 inhibition) in metastatic tumor cells specifically, since normal cells would have low E2F activity, hence would be spared." (PMID 35411090, 2022). "Conversely p27kip, a putative tumor suppressor expression was increased, while the expression of STAT-3 and AKT remain unchanged." (PMID 36224238, 2022). "ablated STAT3 in hematopoietic cells of adult mice with the Mx1‐Cre‐loxP system via injection of poly(I:C), and the anti‐tumor immunity was evaluated." (PMID 35356799, 2022). "In xenograft study, the combination of YHO-1701 (STAT3 inhibitor) and alectinib significantly suppressed tumor regrowth after treatment cessation with near tumor remission compared with alectinib alone." (PMID 35228642, 2022). "GBM tumor cells promote M2 GAM polarization by activation of STAT3, NF-κB, Wnt-3a, and mechanistic target of rapamycin (mTOR), resulting in upregulation of IL-10 levels." (PMID 35572545, 2022). "Pro-inflammatory cytokines (TGF-β, TNF-α, IL-1, IL-6) produced by activated TILs in a hypoxic tumor environment enhance EMT through the NF-ĸB/STAT3 pathway." (PMID 35269636, 2022). "IL-6/JAK/STAT3 signaling strongly inhibits anti-tumor immune response through negative regulatory effects of T cells and natural killer cells, which contributes to the formation of primary immunotherapy resistance." (PMID 35508972, 2022). "An activation loop is formed as STAT3 is transcribed, causing suppression of nearby immune cell activity, also leading to a reduction in IFN-γ and TNF-α in GBM, preventing all anti-tumor activity and creating a pro-immunosuppressive environment." (PMID 36338705, 2022). "These pro-inflammatory cytokines can regulate STAT3 and NF-kB signalling in tumour cells, inducing PD-L1 expression and contributing to immunosuppression in tumours." (PMID 36139540, 2022). "Relative to HCC827R‐CSC‐EVs shNC, HCC827R‐CSC‐EVs shAPE1 resulted in down‐regulated levels of APE1, IL‐6 and p‐STAT3/STAT3 in tumour tissues of Erlotinib‐treated mice (all p < .01)." (PMID 35605028, 2022). "On the other hand, neutrophils/chemerin induced EMT of OSCC also through the JAK2/STAT3 pathway and further promoted tumor migration and invasion via EMT." (PMID 35155249, 2022). "Mechanistically, STAT3 was identified as a target of APN in negatively regulating the anti-tumor activity of CD8+ T cells." (PMID 35530361, 2022). "GBM tumor cells also foster pericytes and endothelial cells to produce more IL-10 and TGFβ by activating the IL-6/STAT3 signaling pathway, thus inciting tumor growth." (PMID 35572545, 2022). "It has been proposed that the JAK/STAT signaling pathway is involved in the development of UCEC, and targeted inhibition of the IL‐6 receptor and its downstream effectors JAK1 and STAT3 significantly reduces UCEC tumor cell growth." (PMID 35244291, 2022). "In conclusion, our in vitro study demonstrated that targeting gp130/JAK/STAT3 signaling attenuates tumor microenvironment mediated chemoresistance in Group 3 MB." (PMID 35159191, 2022). "In vivo experiments revealed that transfection with vectors expressing STAT1 and STAT3 inhibited the Siglec-15 RNAi-induced inhibition on tumor growth and the increases in CD4+/CD8+ ratio." (PMID 35769818, 2022). "With activities controlling the pro‐tumorigenic properties of the IL‐6 cytokine family, STAT3 drives various oncogenic processes affecting cell cycle progression and survival, angiogenesis, tumour invasion and metastasis." (PMID 34618359, 2022). "After downregulation the expression level of P471, STAT3 was found to translocate from nucleus to cytoplasm accompanied by a decrease in phosphorylation levels, which attenuated tumor cell proliferation and migration capacity." (PMID 36231093, 2022).
tumor (continued). "HSP72 and HSP105 on the membrane of TEVs interact with TLR2 and TLR4 on DCs which induced IL-6 secretion by DCs that increased STAT3-dependent MMP-9 transcription activity in cancer cells resulting in tumor invasion." (PMID 36612080, 2022). "Its overexpression suppressed proliferation of CRC cell and tumor growth via the miR-18a/STAT3 axis." (PMID 35350786, 2022). "An increased mir-29 expression can inhibit tumor cell proliferation by decreasing STAT3 expression PMID: 31539114." (PMID 35113040, 2022). "It is seen that transforming growth factor-beta (TGF-β) acts via IL-6 to activate the signal transducer and activator of transcription-3 (STAT-3) in the tumor cells, which requires the soluble IL-6 receptor present in the tumor cells." (PMID 36059323, 2022). "Analyses using Huh7 tumor lysates demonstrated that there was reduced p-STAT3 and MCL1 expression following sorafenib treatment." (PMID 36232407, 2022). "STAT3 plays an important role in many biological functions during the development of human tumor, including proliferation, survival, and inflammation." (PMID 35936759, 2022). "Considering the epidemiological importance of urological cancers as well as multidimensional STAT3 activity in tumor progression and metastasis, we strongly believe that STAT3 is underestimated in urologic oncology." (PMID 36230984, 2022). "Meanwhile, matrix metalloproteinase-2 (MMP-2), another downstream oncogene of STAT3, is also overexpressed in AEG patients and significantly associated with tumor differentiation and pT." (PMID 36225196, 2022). "STAT-3 is primarily responsible for tumor growth, proliferation, and sustenance due to its activity in stromal cells, immune cells, and the tumor microenvironment." (PMID 36359888, 2022). "By overexpressing vascular endothelial growth factor, CD204, CD163, MMPs, and arginase-1 immunomodulatory molecules and releasing immunosuppressive molecules, they promote STAT3 expression and tumor cell growth, and inhibit their antigen presentation function." (PMID 36411434, 2022). "These contrasting data imply dependency on tumor type, stage of the disease, and local microenvironment; Stat3 activation or inactivation can each support disease progression depending on such factors." (PMID 36017196, 2022). "Cancer cell-intrinsic alternatively spliced STAT3 isoforms have opposite roles in driving tumor progression." (PMID 35865518, 2022). "In line with the fact that Ruxo is a well-established JAK1/2 inhibitor, we observed the expected suppression of p-JAK2 and p-STAT3 in tumor (CD45−) cells by Ruxo." (PMID 36008408, 2022). "STAT3 represents an attractive target for cancer intervention due to its importance in tumor development and progression and its ability to interplay with many upstream pathways." (PMID 35625738, 2022). "Among the various STAT members, STAT3 is often overexpressed in tumor cells and tissue samples, and it regulates the expression of many oncogenes that control growth and metastasis." (PMID 35296801, 2022). "STATTIC, a STAT3 inhibitor, can selectively inhibit STAT3 dimerization, activation, and nuclear translocation, induce STAT3-dependent apoptosis in tumor cells, and significantly reduce tumor growth." (PMID 36466838, 2022). "IL-17 promotes tumorigenesis through the production of myeloid-derived suppressor cells (MDSCs) and stimulates IL-6 secretion from stromal tumor cells activating the STAT3 pathway." (PMID 35682971, 2022). "It was indicated that the use of AG490 (a JAK2-specific inhibitor) led to reduced tumor numbers and sizes due to STAT3 blocking in HCC rats." (PMID 36077744, 2022). "The IL-19–neutralizing antibody effectively blocked osteoclast-induced STAT3 activation in IL20RB-expressing tumor cells." (PMID 36006737, 2022). "The JAK2/STAT3 signaling pathway is of significance in the regulation of oxidative stress, cellular autophagy, inflammatory response, and tumor progression." (PMID 36104717, 2022).